UBE2C (ubiquitin conjugating enzyme E2 C)
Diseases named in the same sentence as UBE2C in open-access papers (continued):
Sharing a sentence is not in itself a finding about the gene and the disease.
cervical squamous cell carcinoma (4 papers, 2020 to 2024). A squamous cell carcinoma arising from the cervical epithelium. "According to an analysis of TCGA database, UBE2C was upregulated in various cancers, including BCa and cervical squamous cell carcinoma, and was closely linked to a poor prognosis for patients." (PMID 38949026, 2024). "In this study, we explored the potential role and clinical significance of UBE2C in cervical squamous cell carcinoma (CESC)." (PMID 33396624, 2020). "However, the possible impact of UBE2C on the progression of cervical squamous cell carcinoma (CESC) remains unclear." (PMID 33396624, 2020).
gastric adenocarcinoma (4 papers, 2018 to 2023). "Furthermore, inhibition of UBE2C expression was shown to reduce the level of phosphorylation of AURKA and impair cell viability in gastric adenocarcinoma cells." (PMID 37377594, 2023). "Moreover, UBE2C induces Wnt/β-catenin and PI3K/Akt signaling to regulate phosphorylation levels of Aurora-A for epithelial–mesenchymal transition (EMT) in gastric adenocarcinoma." (PMID 32899896, 2020).
leukemia (4 papers, 2014 to 2024). A malignant (clonal) hematologic disorder, involving hematopoietic stem cells and characterized by the presence of primitive or atypical myeloid or lymphoid cells in the bone marrow and the blood. "Motivated by these considerations, this study aims to investigate the role of UBE2C in leukemia development and its underlying mechanism." (PMID 38637730, 2024). "We reported an overexpression of UBE2C in leukemia patients and cell lines (HL60, THP-1, U937, and KG-1 cells)." (PMID 38637730, 2024). "A xenograft model of leukemia cells were established, and the protein levels of UBE2C, KI-67, and cleaved-caspase 3 were detected by immunohistochemistry." (PMID 38637730, 2024). "Nevertheless, whether UBE2C is overexpressed only in certain subtypes of leukemia warrants future investigation." (PMID 38637730, 2024). "Initially, UBE2C expression in leukemia was analyzed using the Cancer Genome Atlas database." (PMID 38637730, 2024). "In addition, in a leukemia model in which myelodysplastic syndrome mice were used, MYBL2 (MYB proto-oncogene like 2) knockdown also resulted in decreased UBE2C expression." (PMID 29596365, 2018).
neuroblastoma (4 papers, 2012 to 2025). Neuroblastoma (NB) is the most common solid, extracranial childhood tumor. "In contrast, in SMG samples from 6-week-old Th-MYCN+/− mice, most MYCN+ neuroblastoma cells were Ube2c+, expanding in tandem with MYCN-/Prph+ ganglion cells." (PMID 40580553, 2025). "We selected human MYCN as a pan-universal neuroblastoma marker, with Prph and Ube2c signifying uncommitted and malignant neuroblast populations, respectively." (PMID 40580553, 2025). "We identified six genes (DLGAP5, DSCC1, SMO, SNRPD1, SSBP1, and UBE2C) with a vital role in mitosis and these are promising therapeutic targets for neuroblastoma." (PMID 23251412, 2012). "In SMG samples from 2-week-old Th-MYCN+/− mice, most MYCN+ neuroblastoma cells expressed Ube2c." (PMID 40580553, 2025). "Thus, here we examined the prognostic role of UBE2C in neuroblastoma." (PMID 34815392, 2021).
renal cell carcinoma (4 papers, 2021 to 2026). "In renal cell carcinoma (RCC), the topmost two signaling pathways affected by UBE2C are cell cycle and DNA replication pathways." (PMID 36385010, 2022).
adrenocortical carcinoma (3 papers, 2023 to 2024). "In adrenocortical carcinoma, UBE2C expression is positively linked with T helper Th1 and Th2 cells and negatively correlated with Treg, M2 macrophages." (PMID 38577722, 2024). "On the other hand, in adrenocortical carcinoma, UBE2C expression is positively linked with T helper Th1 and Th2 cells and negatively correlated with regulatory T cells and M2 macrophage infiltration." (PMID 37958776, 2023). "In conclusion, this study identified UBE2C as a novel oncogenic gene in promoting adrenocortical carcinoma progression and contributing to its poor prognosis." (PMID 37535572, 2023). "Transwell assay results demonstrated that UBE2C siRNAs stimulation remarkably suppressed the invasion of adrenocortical carcinoma cell compared to treated with a scramble siRNA." (PMID 37535572, 2023). "In conclusion, these results demonstrated that UBE2C knockdown can weaken proliferation, migration, and invasion of adrenocortical carcinoma cell via inhibiting cycle progression and EMT." (PMID 37535572, 2023). "UBE2C depletion in adrenocortical carcinoma cells suppresses cell invasion and migration by EMT inhibition, DNA damage repair, and induction of apoptosis." (PMID 37958776, 2023). "Morphological changes of SW-13 cells showed that transfected with control or UBE2C siRNAs strongly inhibited proliferation of adrenocortical carcinoma cell." (PMID 37535572, 2023). "And then the effect of UBE2C on migration and invasion in adrenocortical carcinoma cell were further investigated." (PMID 37535572, 2023). "Systematic investigation of the tumorigenic effect of UBE2C may help in understanding its prognostic value in adrenocortical carcinoma." (PMID 37535572, 2023). "At first, we assessed the effects of UBE2C on adrenocortical carcinoma cell growth." (PMID 37535572, 2023). "Moreover, in vitro experiments showed that UBE2C knockdown result in poor prognosis of ACC by inhibiting the proliferation, migration, invasion, epithelial–mesenchymal transition (EMT) of adrenocortical carcinoma cells as well as the cell cycle progression." (PMID 37535572, 2023). "However, the tumorigenic effect and mechanism of UBE2C in adrenocortical carcinoma (ACC) remains unclear." (PMID 37535572, 2023). "In addition, UBE2C knockdown could significantly inhibit the proliferation, migration, invasion, EMT of adrenocortical carcinoma cells as well as the cell cycle progression in vitro." (PMID 37535572, 2023).
malignant glioma (3 papers, 2020 to 2022). A grade III or grade IV glioma arising from the central nervous system. "High expression of UBE2C is associated with the tumor progression and unfavorable outcome in patients with malignant glioma." (PMID 32899896, 2020). "Increased expression of UBE2C (F = 9.92, p = 1.28 × 10−10) observed in ST_EPN_RELA of the Pfister dataset has been associated with aggressive progression and poor outcome of malignant glioma." (PMID 36293188, 2022).
oral cancer (3 papers, 2020 to 2023). "Moreover, high co-expression of UBE2C/CD44, UBE2C/CD166 and UBE2C/EpCAM was associated with recurrence in oral cancer patients including TSCC patients." (PMID 32899896, 2020). "We evaluated the effects of UBE2C knockdown on the migration, invasion, colony formation and proliferation abilities of oral cancer cells." (PMID 35615976, 2022). "The regulation pathway of UBE2C-modulating cancer stemness will be further validated in oral cancer patient." (PMID 32899896, 2020). "High co-expression levels of UBE2C/CD44, UBE2C/CD166 and UBE2C/EpCAM were associated with poor prognosis in oral cancer patients from The Cancer Genome Atlas database." (PMID 32899896, 2020). "Nevertheless, we further found that high co-expression of UBE2C and cancer stemness markers, including CD44, D166 and EpCAM, have even worse poor prognosis in TSCC patients, which provided potential diagnostic and prognostic markers in oral cancer patients." (PMID 32899896, 2020). "Furthermore, The Cancer Genome Atlas (TCGA) oral cancer cohorts with co-expression level of high UBE2C/cancer stemness markers had poor prognosis." (PMID 32899896, 2020). "Moreover, high coexpression of UBE2C/CD44, UBE2C/CD166 and UBE2C/EpCAM genes was associated with overall survival and recurrence in oral cancer patients including TSCC patients from TCGA database, indicating that UBE2C might be involved in controlling cancer stemness of OSCC." (PMID 32899896, 2020).
pneumonia (3 papers, 2022 to 2024). An acute, acute and chronic, or chronic inflammation focally or diffusely affecting the lung parenchyma, caused by an infection in one or both of the lungs (by bacteria, viruses, fungi, or mycoplasma.). "A study of peripheral blood transcriptome sequencing in patients with pneumonia found that the expression of UBE2C in patients with severe pneumonia was higher than that in patients with mild pneumonia." (PMID 39371335, 2024). "A transcriptome sequencing study of the peripheral blood of patients with pneumonia found that the expression of UBE2C in patients with severe pneumonia is higher than that in patients with mild pneumonia." (PMID 36551164, 2022).
triple-negative breast carcinoma (3 papers, 2019 to 2023). An invasive breast carcinoma which is negative for expression of estrogen receptor (ER), progesterone receptor (PR), and human epidermal growth factor receptor 2 (HER2). "Compared to normal tissues in BRCA tumors, the expression of UBE2C was higher in all different subtypes, including triple negative breast cancer (TNBC), HER2-amplification, and luminal subtype." (PMID 31067633, 2019).
uterine cancer (3 papers, 2016 to 2024). Primary or metastatic malignant neoplasm involving the uterine corpus and/or the cervix. "Based on our analysis, the highest genetic alteration frequency of UBE2C occurs in colorectal adenocarcinoma and uterine carcinoma, respectively." (PMID 38577722, 2024). "Also, UBE2C expression is high in lung, stomach, and uterine cancer compared with surrounding normal tissues." (PMID 27528424, 2016). "More interestingly, it has been reported that overexpression of the ubiquitin-conjugating enzyme E2C (UBE2C) is a typical feature of a number of cancer cell lines and primary tumors, including lung, gastric, bladder, and uterine cancers." (PMID 30486251, 2018).
uterine carcinosarcoma (3 papers, 2022 to 2024). A usually aggressive malignant neoplasm arising from the uterine corpus and less often the cervix. "The genetic alteration frequency of UBE2C in uterine carcinosarcoma is nearly as high." (PMID 38577722, 2024).
uterine corpus endometrial carcinoma (3 papers, 2022 to 2024). A endometrial carcinoma (disease) that involves the body of uterus. "Also, upregulated UBE2C expression was significantly correlated with poor prognosis and disease free survival (DFS) of patients with ACC, KIRC, KIRP, LGG, LIHC, MESO, PAAD, Prostate adenocarcinoma (PRAD), THCA, Uterine corpus endometrial carcinoma (UCEC), and UVM." (PMID 38577722, 2024).
acute myeloid leukemia (2 papers, 2022 to 2024). Acute myeloid leukemia (AML) is a group of neoplasms arising from precursor cells committed to the myeloid cell-line differentiation. "This study aims to investigate the role and mechanism of tubiquitin-conjugating enzyme E2 C (UBE2C) in acute myeloid leukemia (AML)." (PMID 38637730, 2024).
brain tumors (2 papers, 2023). "Dactolisib-treated brain tumors exhibited a significant decrease in the number of cancer cells expressing high levels of UBE2C." (PMID 37215954, 2023). "In this review, we aim to discuss the role of UBE2C in brain cancer invasion and dissemination and its potential therapeutic targeting in brain tumor patients." (PMID 37958776, 2023). "The overexpression of UBE2C has been described in many human cancers, namely breast, lung, thyroid, endometrial, renal, prostate, pancreatic, esophageal, hepatocellular, gastrointestinal, and brain tumors." (PMID 37958776, 2023). "In UBE2C-depleted tumors, dactolisib did not significantly impact brain tumor size or CNS dissemination." (PMID 37215954, 2023).
cholangiocarcinoma (2 papers, 2020 to 2023). A carcinoma that arises from the intrahepatic biliary tree (intrahepatic cholangiocarcinoma) or from the junction, or adjacent to the junction, of the right and left hepatic ducts (hilar cholangiocarcinoma). "We validated that ubiquitination-associated gene UBE2C had the highest expression in cholangiocarcinoma patients’ tumors." (PMID 38102624, 2023). "Retrospective analysis determined that UBE2C expression was significantly associated with surgical margin, primary tumor, histological variant, and histological grade in cholangiocarcinoma patients." (PMID 38102624, 2023). "Taken together, these analyses indicated that UBE2C might provide a new diagnostic marker for cholangiocarcinoma." (PMID 38102624, 2023). "Moreover, to further determine the association between the prognostic significance of UBE2C expression and clinicopathological parameters in cholangiocarcinoma patients, we performed univariate and multivariate analyses." (PMID 38102624, 2023). "More specifically, high expression of UBE2C was negatively associated with overall survival, disease-specific survival, local recurrence-free survival, and metastasis-free survival in patients with cholangiocarcinoma." (PMID 38102624, 2023). "In this report, we mined the published cholangiocarcinoma transcriptome data set (GSE26566), compared it with the ubiquitination-associated gene (GO:0016567), and identified that UBE2C was highly expressed in cholangiocarcinoma tumor tissue." (PMID 38102624, 2023). "We observed that the low-stage cholangiocarcinoma tumor tissues had weak UBE2C expression, whereas the high-stage cholangiocarcinoma tumor tissues had strong UBE2C expression." (PMID 38102624, 2023). "We attempted to clarify the effect of UBE2C expression on the development of cholangiocarcinoma and demonstrated that UBE2C may act as a prognostic factor in cholangiocarcinoma." (PMID 38102624, 2023). "We found that UBE2C expression was negatively correlated with overall survival, disease-specific survival, local recurrence-free survival, and metastasis-free survival in patients with cholangiocarcinoma." (PMID 38102624, 2023). "We found that the ubiquitination-associated gene, UBE2C, is most highly expressed in cholangiocarcinoma tumor tissue compared with non-tumor biliary epithelium tissue." (PMID 38102624, 2023). "Our findings demonstrate that UBE2C may provide a potential therapeutic marker and prognostic factor for cholangiocarcinoma patients." (PMID 38102624, 2023). "Moreover, we determined the expression of UBE2C in human cholangiocarcinoma tumor tissues by immunohistochemical (IHC) staining." (PMID 38102624, 2023). "Taken together, these results suggested that UBE2C may serve as a prognostic marker of cholangiocarcinoma." (PMID 38102624, 2023). "Moreover, we further investigated the correlation between UBE2C expression and clinicopathological characterization in cholangiocarcinoma patients." (PMID 38102624, 2023). "This study is the first to illustrate that UBE2C may be a potential marker for evaluating the prognosis of cholangiocarcinoma patients." (PMID 38102624, 2023). "However, the expression of UBE2C in survival outcomes and prognosis of cholangiocarcinoma patients is still unclear." (PMID 38102624, 2023). "Therefore, these analyses suggest that UBE2C may provide a reliable potential marker for cholangiocarcinoma patients." (PMID 38102624, 2023). "Furthermore, we demonstrated that high expression of UBE2C was significantly correlated with poor overall survival, disease-specific survival, local recurrence-free survival, and metastasis-free survival in patients with cholangiocarcinoma." (PMID 38102624, 2023). "To understand the undisclosed functions of UBE2C in IHCC, we downloaded the top 200 differentially expressed genes presenting a positive relationship or a negative relationship to UBE2C from the cholangiocarcinoma data set (TCGA, Firehose Legacy, n = 51)." (PMID 38102624, 2023).
cholangiocarcinoma (continued). "We noted that among these genes, UBE2C (Ubiquitin-conjugating enzyme E2 C) showed the highest fold change in expression between the cholangiocarcinoma tumor tissue and non-cancerous livers (log2 ratio = 1.7925; p-value < 0.0001)." (PMID 38102624, 2023). "Our study indicated that UBE2C protein expression was significantly increased in cholangiocarcinoma tumor tissues compared to non-tumor tissues by immunohistochemistry." (PMID 38102624, 2023). "However, there is currently no relevant literature to indicate whether UBE2C is related to the clinical survival outcome of cholangiocarcinoma patients." (PMID 38102624, 2023).
diffuse large B-cell lymphoma (2 papers, 2018 to 2022). "Applying the Bonferroni correction method to identify false positive results, the significance of FOXM1 and UBE2C expression correlation is maintained in all tumors analysed, except for lymphoid neoplasm diffuse large B-cell lymphoma." (PMID 29596365, 2018).
hepatoblastoma (2 papers, 2023). Hepatoblastoma (HB) is a malignant hepatic tumor and is the most common pediatric liver cancer. "In hepatoblastoma clinical samples, high levels of UBE2C mRNA seem to increase distant metastasis and death rates." (PMID 37958776, 2023). "Moreover, the knockdown of UBE2C in the HuH6 hepatoblastoma cell line and in the HB-243 cell line from a patient-derived xenograft decreased cell viability by up to 44% and cell migration by 65%." (PMID 37958776, 2023).
infiltrating ductal carcinoma (2 papers, 2013 to 2019). "In addition, UBE2C expression in BRCA showed high levels in all histological subtypes, with the most significant increase in infiltrating lobular carcinoma (ILC) and infiltrating ductal carcinoma (IDC)." (PMID 31067633, 2019).
lung adenoma (2 papers, 2020 to 2023). A benign, well circumscribed epithelial neoplasm that arises from the bronchus or the lung parenchyma. "H&E staining analysis revealed that while mice with Ube2c deletion alone [Kras(–)Ube2c–/–] had normal lung development without any tumor formation, the WT mice [Kras(+)Ube2c+/+ or Kras(+)Ube2c+/–] developed, as expected, multiple lung adenomas with few adenocarcinomas." (PMID 36548081, 2023).
Obesity (2 papers, 2021 to 2024). Accumulation of substantial excess body fat. "Specifically, the expression of UBE2C was significantly lower in the Extreme Obesity group compared to the Normal Weight group (p=4.0e-07), Overweight group (p =4.63e-04), and Obese group (p = 1.83e-03)." (PMID 38370368, 2024). "Although there have been no reports on the relationship between UBE2C and obesity, we suppose that UBE2C might be a novel target of GTE, and further study is needed to confirm this hypothesis." (PMID 33946279, 2021).
osteosarcoma (2 papers, 2020). A usually aggressive malignant bone-forming mesenchymal neoplasm, predominantly affecting adolescents and young adults. "Moreover, the downregulation of UBE2C suppresses cell proliferation in osteosarcoma by decreasing the expression of the cell cycle-related protein Ki-67." (PMID 32899896, 2020).
psoriasis (2 papers, 2024 to 2025). An autoimmune condition characterized by red, well-delineated plaques with silvery scales that are usually on the extensor surfaces and scalp. "Ubiquitin-conjugating enzyme E2 C (UBE2C) is a hub gene might have a role in development and progression of the psoriasis." (PMID 38795139, 2024).